CIAO2B (cytosolic iron-sulfur assembly component 2B)
Description:
Component of the cytosolic iron-sulfur protein assembly (CIA) complex, a multiprotein complex that mediates the incorporation of iron-sulfur cluster into extramitochondrial Fe/S proteins. As a CIA complex component and in collaboration with CIAO1 and MMS19, binds to and facilitates the assembly of most cytosolic-nuclear Fe/S proteins. As part of the mitotic spindle-associated MMXD complex it plays a role in chromosome segregation, probably by facilitating iron-sulfur cluster assembly into ERCC2/XPD. Together with MMS19, facilitates the transfer of Fe-S clusters to the motor protein KIF4A, which ensures proper localization of KIF4A to mitotic machinery components to promote the progression of mitosis.
Synonyms: FAM96B; MIP18; CGI-128; CIA2B
Tractability: PROTAC: ubiquitination databases record sites on it.
Gene: Protein-coding gene on chromosome 16 (66,932,065 to 66,934,423, reverse strand). Ensembl gene ENSG00000166595.
Subcellular location: Nucleus; Cytoplasm, cytoskeleton, spindle; Midbody
Subcellular location (Human Protein Atlas): Cytosol; Nucleoplasm
Pathways (Reactome):
Metabolism: Cytosolic iron-sulfur cluster assembly
Gene Ontology:
Molecular function: protein binding
Biological process: chromosome segregation; protein maturation; iron-sulfur cluster assembly
Cellular component: cytoplasm; cytosol; cytosolic [4Fe-4S] assembly targeting complex; midbody; MMXD complex; nucleoplasm; nucleus; spindle
Genetic constraint (gnomAD): Loss-of-function variants: 20 observed, 17.1 expected, observed/expected ratio (o/e) 1.17, 90% interval 0.82 to 1.68. The upper end of that interval is the gene's LOEUF score, 1.68, which puts it in group 6 of 6, group 1 being the genes least tolerant of losing a copy. Missense variants: 215 observed, 217.25 expected, observed/expected ratio (o/e) 0.99, 90% interval 0.88 to 1.11. Synonymous variants: 106 observed, 88.46 expected, observed/expected ratio (o/e) 1.2, 90% interval 1.02 to 1.41.
Homologues: Orthologues: pig CIAO2B (99% identical), dog CIAO2B (99% identical), macaque CIAO2B (99% identical), chimpanzee CIAO2B (98% identical), mouse Ciao2b (98% identical), rat Ciao2b (98% identical), guinea pig CIAO2B (97% identical), tropical clawed frog ciao2b (84% identical), zebrafish ciao2b (81% identical), Drosophila melanogaster galla-2 (66% identical), Caenorhabditis elegans ciao-2B (57% identical). Paralogues in human: CIAO2A (42% identical).
Diseases named in the same sentence as CIAO2B in open-access papers:
CIAO2B is named in the same sentence as 14 diseases in open-access papers, as found by Europe PMC text mining. Sharing a sentence is not in itself a finding about the gene and the disease. The quoted sentences say what the papers report.
cancer (3 papers, 2021 to 2024). A tumor composed of atypical neoplastic, often pleomorphic cells that invade other tissues. "Members of the cytosolic Fe/S assembly pathway- MMS19 and CIAO2B were found to be essential for replication stress tolerance of cancer cells towards Chk1 and ATR inhibition." (PMID 37810966, 2023).
CIAO2B also shares sentences with these, for which no sentence is quoted: infection (7 papers); breast carcinoma (2); metabolic disease (2); tumor (2); campylobacteriosis (1); colon cancer (1); diarrhoea (1); enteritis (1); hepatocellular carcinoma (1); hyperlipidemia (1); liver cancer (1); Obesity (1); xeroderma pigmentosum (1).